AARS1 (alanyl-tRNA synthetase 1)
Diseases named in the same sentence as AARS1 in open-access papers (continued):
Sharing a sentence is not in itself a finding about the gene and the disease.
tumor (27 papers, 2015 to 2026). "In contrast, an NLS-deleted mutant AARS1 failed to lactylate targets and rescue the suppression of cell proliferation and tumor formation caused by AARS1 knockout, indicating that nuclear localization is required for AARS1’s oncogenic role." (PMID 41008630, 2025). "In addition, AARS1 showed significantly positive association with the dominant pathways of the Hot tumor cluster, including apoptosis, base excision repair, mismatched repair, VEGF signaling, ERBB signaling, etc.." (PMID 36991000, 2023). "Spatial transcriptomics data from the HCCDB database confirmed relatively higher AARS1 expression in tumour regions versus para‐tumour regions." (PMID 41454479, 2026). "Differential expression analysis showed higher AARS1 mRNA levels in most tumour types, including HCC, compared to adjacent normal tissues." (PMID 41454479, 2026). "Further investigation is required upon targeting the nuclear translocation of AARS1 to reverse the tumor-promoting lactylation." (PMID 41008630, 2025). "Meanwhile, AARS1/2 act as fundamental lactyltransferases to catalyze global lysine lactylation during tumor progression." (PMID 41008630, 2025). "Excitingly, it has been reported that inhibiting the lactylase enzyme AARS1 with β-alanine effectively slowed tumor progression." (PMID 41373440, 2025). "Other lactyltransferases have been recently identified that AARS1 mediates global lysine lactylation, thereby promoting tumor progression." (PMID 40113760, 2025). "As a major finding of this current work, we unambiguously identified AARS1 as a lactyltransferase able to catalyze protein lactylation using free lactate and ATP, which are abundant in cells, especially in proliferating tumor cells." (PMID 38512451, 2024). "In tumor and adjacent normal tissues, we confirmed that AARS1-overexpressing tumors exhibited K-Ala modification on PARP1." (PMID 36991000, 2023). "Using western blot and immunohistochemistry (IHC), we confirmed that AARS1 protein levels were enhanced in tumor tissues during DC carcinogenesis (t-test, p = 6.7E−8)." (PMID 36991000, 2023). "Besides, the newly-reported targeting strategy also aims to block AARS1, which serves as a bridge linking tumor cell metabolism with proteomic changes." (PMID 39934144, 2025). "Blocking the nuclear translocation of AARS1 may significantly affect oncogenic lactylation modification in tumor cells while having fewer effects on normal cell metabolism with lactate." (PMID 41008630, 2025).
tumor (continued). "This contrast underscores the context-dependent nature of lactylation and ubiquitination crosstalk, where AARS1 can either facilitate or suppress ubiquitination depending on the substrate, highlighting the complexity of post-translational regulation in tumor biology." (PMID 41008630, 2025). "Given the clinical relevance and the tumor-promoting role of AARS1, we further analyzed AARS1 mutations in the COSMIC and cBioPortal databases and found that R77Q was the most common AARS1 mutation in patients with GC." (PMID 38512451, 2024). "To investigate whether AARS1 promotes tumor cell growth in a manner dependent on the Hippo pathway, we performed an RNA-Seq analysis of AARS1-knockdown HGC27 cells." (PMID 38512451, 2024). "To further investigate the pathological function of AARS1 in tumorigenesis, we generated subcutaneous and orthotopic mouse GC models and found that knockdown of AARS1 markedly inhibited tumor growth, while enforced expression of YAP-TEAD1 abolished this inhibitory effect." (PMID 38512451, 2024). "Next, we assessed the potential regulatory effect of AARS1 on YAP-driven tumor growth." (PMID 38512451, 2024). "Since glucose is metabolized to lactate during aerobic glycolysis, this dual sensing mechanism of glucose and lactate by YAP and AARS1, respectively, may further enforce the interpretation of metabolic and nutrient cues into tumor cell proliferation signals." (PMID 38512451, 2024). "In addition, we found the expression level of AARS1 increased significantly in tumor tissues, and growingly enhanced during DC progression." (PMID 36991000, 2023). "Furthermore, AARS1/2, typically catalyzes the ligation of l-alanine to transfer RNA, were recently identified as the general lysine lactyltransferase that senses lactate and mediates global lysine lacylation in tumor cells in an ATP-dependent manner." (PMID 40849487, 2025). "Thus, we speculated AARS1, growingly increased during the tumor progression of DC and along with enhanced DNA damage, was a potential target in the clinic strategy of DC." (PMID 36991000, 2023). "In addition, we noted that increased AARS1 expression promoted the xenograft growth of tumor cells, especially in HU-treated cell xenografts in nude mice, whereas inhibition of K-Ala with alaninol delayed the xenograft growth of tumor cells." (PMID 36991000, 2023). "As AARS1 itself is one of the downstream target genes, AARS1 and YAP-TEAD1 form a positive feedback loop in the context of lactate during tumor progression." (PMID 41008630, 2025). "In our current study, AARS1 expression was found to be upregulated in tumor tissues from patients with GC and MNU-induced GC mouse models, and this upregulation was consistent with our findings that AARS1 served as a direct target gene of YAP-TEAD1." (PMID 38512451, 2024). "Consistently, mice orthotopically injected with HGC27 cells stably expressing AARS1 had larger tumors in their stomachs than the control group, whereas silencing the expression of YAP-TEAD1 abrogated AARS1 overexpression–induced tumor growth." (PMID 38512451, 2024). "We illuminated the drug-targetable AARS1 in the TMB/immune infiltration in DC, which was demonstrated the value of this multi-omics mapping strategy to suppress tumor growth." (PMID 36991000, 2023). "This nonclassical function of AARS1 links the high levels of lactate in tumor cells to the YAP‐driven malignant proliferation signaling, offering a new perspective for understanding the Warburg effect in tumor cells." (PMID 40443721, 2025).
tumor (continued). "Additionally, alanyl-tRNA synthetase 1 (AARS1) acts as an intracellular lactate receptor and a lactyltransferase responsible for global lysine lactylation in tumor cells." (PMID 41152975, 2025). "Given the competitive binding of lactate and alanine to AARS1, this explains why high lactate levels do not inhibit general mRNA translation, which is essential for cell proliferation and tumor growth." (PMID 39897556, 2025). "AARS1 catalyzes the lysine-alanylation (K-Ala) of poly (ADP-ribose) polymerase 1 (PARP1) in K621 peptides, suppressing PARP1 activity and cell apoptosis, thereby promoting tumor growth." (PMID 41008630, 2025). "In the case of AARS1-mediated lactylation of the Hippo pathway, AARS1 and YAP-TEAD form a positive-feedback loop that constitutively pushes forward the conversion of lactate metabolism into tumor cell growth." (PMID 38512451, 2024). "The referred significant proteins in the DNA repair panel, especially AARS1 and TARS2, were significantly and highly expressed in the Hot tumor cluster, and were overrepresented in the tumor tissue both in the D and G subtypes, implying their potential value in the clinic strategy." (PMID 36991000, 2023). "Moreover, we found that in response to intracellular accumulation of lactate, AARS1 translocated into the nucleus, where it directly catalyzed lactylation of YAP at K90 and TEAD1 at K108, thereby activating downstream target gene expression to promote tumor cell proliferation." (PMID 38512451, 2024). "Notably, PCAF promoted, whereas AARS1 did not affect, RHOA lactylation, highlighting the substrate-dependent regulation of lactylation; HDAC3 acts as a metabolic checkpoint, dynamically balancing lactylation levels to modulate RHOA signaling in tumor microenvironments." (PMID 41291745, 2025).
cancer (15 papers, 2015 to 2026). A tumor composed of atypical neoplastic, often pleomorphic cells that invade other tissues. "Affinity chromatography, mass spectrometry and in vitro studies in HGC27 cancer cells via loss-of-function and gain-of-function approaches identified alanyl-tRNA synthetase 1 (AARS1), a bona fide lactyl-transferase, which directly uses lactate and ATP to catalyze protein lactylation." (PMID 39516356, 2024). "Dysregulation of AARS1/2 contributes to various cancer hallmarks like metabolic reprogramming, uncontrolled proliferation, immune escape, and therapy resistance in a lactylation-driven manner." (PMID 41008630, 2025). "It is of significance to identify the tissue- or cancer-specific functions of AARS1 and AARS2, extending beyond their canonical roles in protein synthesis, particularly concerning the novel regulatory mechanism of lactylation." (PMID 41008630, 2025). "Current research has highlighted AARS1/2 as lactate sensors and lactyltransferases that catalyze global lysine lactylation in cancer cells and promote cancer proliferation, providing a new perspective for cancer therapy." (PMID 41008630, 2025). "AARS1 mediates global lysine lactylation and transduces high levels of lactate into cell proliferation signals in cancers." (PMID 41008630, 2025). "This approach highlights the significance of validating the role of AARS1/2 in lactylation-driven cancer therapy resistance." (PMID 41008630, 2025). "Targeting AARS1/2 or their lactylation-driven oncogenic signaling pathways represents a promising, novel therapeutic strategy for cancers." (PMID 41008630, 2025). "AARS1 knockdown significantly suppresses cancer cell proliferation in vitro and tumorigenesis in vivo." (PMID 41008630, 2025). "For example, the clinical relevance of AARS1 to various GC subtypes as well as to other types of malignant tumors remains to be clarified." (PMID 38512451, 2024). "Lysine lactylation mediated by AARS1/2 has emerged as a direct molecular link between cellular metabolism and oncogenic signaling, which could serve as novel biomarkers for cancer treatment response." (PMID 41008630, 2025). "However, the roles of lactylation and AARS1/2 in other cancer resistance pathways are unclear, thus requiring further investigation and remaining a promising future direction." (PMID 41008630, 2025). "In proliferating cancer cells addicted to aerobic glycolysis, the intracellular lactate may accumulate to high levels and promote the expression of AARS1, which in turn increases the cellular activity of AARS1 as both lactyltransferase and a tRNA synthetase." (PMID 38512451, 2024). "The nuclear localization of wild-type AARS1 promotes the lactylation of YAP and TEAD, activating the Hippo pathway and promoting cancer cell proliferation." (PMID 41008630, 2025). "Therefore, specific identification of AARS1/2 expression and lactylation-related function across different tissues and cancer types is essential to offer novel, context-dependent therapeutic targets for cancer and other diseases driven by AARS1/2 dysregulation." (PMID 41008630, 2025). "In summary, this review highlights the novel lactylation-dependent roles of AARS1 and AARS2 in cancers that extend beyond their canonical functions in protein synthesis." (PMID 41008630, 2025). "We observed increased lactate and lactylation levels in anthracycline-resistant cancer cells and proposed a novel mechanism by which hyperlactylation of BLM by AARS1 promoted anthracycline resistance by activating HR repair in cancer cells." (PMID 40634292, 2025).
cancer (continued). "Therefore, deepening our molecular understanding of AARS1/2 lactylation profiles and intensifying further research aimed at developing lactylation regulators or specific inhibitors are urgently needed to translate this mechanism into effective cancer therapies." (PMID 41008630, 2025). "We found that the siRNA-mediated knockdown of AARS1, a novel lactate sensor and lactyltransferase, inhibited BLM lactylation in E-resistant cancer cells." (PMID 40634292, 2025). "AARS1 and AARS2 are generally upregulated in many cancers, consistent with increased protein synthesis demand." (PMID 41008630, 2025). "Targeting the regulatory mechanisms controlling the oncogenic functions of AARS1 and AARS2, particularly lactylation-related mechanisms, holds promising therapeutic potential for cancers but requires confronting challenges by developing isoform-specific and function-specific inhibitors." (PMID 41008630, 2025). "Existing evidence suggests that AARS1/2 catalyze lactylation, but tissue/cancer-specific identification is lacking." (PMID 41008630, 2025). "Interestingly, β-alanine treatment substantially inhibits the proliferation of cancer cells, while AARS1 depletion does not have adverse effects on impeding protein synthesis." (PMID 40128358, 2025). "Moreover, we revealed that high expression of AARS1 promoted RAD51 chromatin accumulation and decreased γH2AX expression in E-resistant cancer cells overexpressing BLM-WT rather than the K24R mutant." (PMID 40634292, 2025).
peripheral neuropathy (7 papers, 2016 to 2025). A disorder affecting the peripheral nervous system. "During the last nine years, about 1,000 individuals with suspected peripheral neuropathy have been tested for mutations in AARS1 at Telemark Hospital." (PMID 35971119, 2022). "Proteomic analyses based on of PBMC from four CMT-affected individuals suggest that involvement of inflammation and mitochondrial dysfunction might contribute to AARS1 variant-associated peripheral neuropathy." (PMID 35971119, 2022).
infection (3 papers, 2015 to 2025). The state of being infected such as from the introduction of a foreign agent such as serum, vaccine, antigenic substance or organism. "To query the impact of AlaRS functions on the proteome and lactylation state during infection with HCMV, we used two parallel approaches: (i) treatment of wild-type (WT) fibroblasts with 100 mM alanine compared to untreated cells and (ii) AARS1 KD compared to a scramble control." (PMID 39772686, 2025).
AARS1 also shares sentences with these, for which no sentence is quoted: malaria (6 papers); Ataxia (3); cardiomyopathy (3); genetic diseases (3); neurologic disorders (3); colorectal cancer (2); distal hereditary motor neuropathy (2); distal motor neuropathy (2); encephalopathies (2); interstitial lung disease (2); microcephaly (2); mitochondrial disease (2); myopathies (2); polyneuropathies (2); tuberculosis (2); albinism (1); Alkalosis (1); Alzheimer disease (1); Atrophy (1); brain disease (1); brucellosis (1); central nervous system diseases (1); cerebellar ataxia (1); Charcot Marie Tooth type 2 (1); clear cell renal cell carcinoma (1); Cognitive impairment (1); COVID-19 (1); cryptosporidiosis (1); developmental delays (1); early infantile epileptic encephalopathy-29 (1).
A further 29 diseases each share a sentence with AARS1 in 1 paper.